MYC (MYC proto-oncogene, bHLH transcription factor)
Diseases named in the same sentence as MYC in open-access papers (continued):
Sharing a sentence is not in itself a finding about the gene and the disease.
hepatocellular carcinoma (continued). "The findings that MYC expression was repressed in the human hepatoma cell lines under extremely low oxygen concentrations may partly responsible for this non-significance." (PMID 19948069, 2009). "FGF19 could cooperate with MYC to promote hepatocellular carcinoma development." (PMID 40478912, 2025). "In hepatocellular carcinoma (HCC), overexpression of MYC is closely related to cell cycle progression and apoptosis, and inhibition of MYC can significantly improve the sensitivity of HCC cells to chemotherapy." (PMID 40290723, 2025). "In hepatocellular carcinoma (HCC), high FBL, MYC, and E2F levels are linked to lung metastases and poor prognosis." (PMID 41463151, 2025). "Another suggested mechanism was through the activation of the nuclear RNA helicase MTR4 transcription by MYC in hepatocellular carcinoma (HCC)." (PMID 40126351, 2025). "MYC is a key oncogenic transcriptional factor driving hepatocellular carcinoma progression, and a copy number amplification of chromosome 8q24, where it is located, is known to be a molecular event contributing to the elevated expression levels and enhanced activity of MYC in HCC." (PMID 38862581, 2024). "We retrieved the Cancer Genome Atlas–Liver Hepatocellular Carcinoma (TCGA-LIHC) dataset and analyzed the correlation between the c-MYC activation status and TSC1/2 mutation status in human HCC." (PMID 39325536, 2024). "In addition, knockdown of MYC significantly reduces proline and hydroxyproline production in hepatocellular carcinoma cells under hypoxic conditions, indicating that the glutamine metabolic axis via MYC/GLS and MYC/ALDH18A1 is essential for proline synthesis under hypoxic conditions." (PMID 39051546, 2024). "Similarly, in hepatocellular carcinoma (HCC), p300 has been implicated in the significant reprogramming of super‐enhancers, leading to the upregulation of critical oncogenes, including MYC, MYCN, and CCND1, and fostering cancer cell proliferation both in vitro and in vivo." (PMID 38374872, 2024). "In 2018, the therapeutic effect of IL-12 mRNA-LNPs on MYC oncogene-driven hepatocellular carcinomas (HCC) was verified." (PMID 36839944, 2023). "miR-744 was a potential prognostic marker for patients with liver cancer and inhibited the growth of Hepatocellular carcinoma (HCC) cells by targeting c-MYc." (PMID 36922987, 2023). "Leveraging IGD biology, epigenomic controllers targeted the IGD containing MYC were able to robustly downregulate expression of the gene across both hepatocellular carcinoma (HCC) and non-small cell lung cancer (NSCLC) cell lines." (PMID 36631803, 2023). "Moreover, we found that FBL might be involved in the regulation of MYC and E2F pathways in hepatocellular carcinoma." (PMID 36004921, 2022). "A study on hepatocellular carcinoma (HCC) identified lncCSMD1-1 upregulated in HCC and directly binding to the MYC protein in the nucleus of HCC cells, promoting HCC progression and the upregulation of MYC protein." (PMID 36553598, 2022). "Recent studies identified distinct enhancers of MYC in various cancers, but any MYC enhancer(s) in hepatocellular carcinoma (HCC) remain(s) elusive." (PMID 35039581, 2022). "Indeed, the ectopic, over-expression of MYC alone is sufficient to initiate and necessary to maintain tumor growth in numerous mouse models, including those of lymphoma, breast cancer, osteosarcoma and hepatocellular carcinoma." (PMID 36552737, 2022). "In an effort to exploit MYC as a therapeutic target, including in hepatocellular carcinoma (HCC), strategies have been developed on the basis of MYC amplification or gene translocation." (PMID 30833661, 2019). "In addition to drive cancer initiation, MYC is also responsible for its maintenance: in several MYC-driven mouse tumor models, blocking MYC activity elicits tumor regression by promoting growth arrest and apoptosis and inducing cell differentiation, such as in sarcoma and hepatocellular cancer." (PMID 28217689, 2017).
hepatocellular carcinoma (continued). "Since the 1980s, c-MYC studies have focused on its role in liver carcinogenesis—hepatocellular carcinoma (HCC)." (PMID 28422055, 2017). "Overexpression of MYC has been found in various types of human cancers, including hepatocellular carcinoma (HCC), the most common type of liver cancers." (PMID 27549025, 2016). "Therefore c-MYC is an attractive target in developing new therapies for hepatocellular carcinoma." (PMID 26286633, 2015). "We investigated the prognostic value of hypoxia-inducible factor-1 alpha (HIF-1alpha) in hepatocellular carcinoma (HCC), and its correlations with inflammation, angiogenesis and MYC oncogene." (PMID 19948069, 2009). "The TRE-LAP MYC transgenic mice over-express human MYC in liver cells upon removal of doxycycline from the drinking water resulting in hepatocellular carcinoma (HCC) in neonates from pregnant females." (PMID 18628958, 2008). "MYC-targeted WDR4 promoted proliferation, metastasis and sorafenib resistance by inducing CCNB1 translation in hepatocellular carcinoma." (PMID 40303931, 2025). "Here, we demonstrate that knockout of Npc1 in hepatocytes attenuates hepatocellular carcinoma (HCC) progression in both DEN (diethylnitrosamine)-CCl4 induced and MYC-driven HCC mouse models." (PMID 39762312, 2025). "Consistent with the results of bulk RNA sequencing data analysis, cell proliferation-associated pathways, such as E2F targets, G2M checkpoint, and MYC targets signaling, were significantly enriched in ESCO2-positive hepatoma cells." (PMID 40657363, 2025). "In hepatocellular carcinoma, MYC binds to PD-L1 and increases its expression, promoting an immunosuppressive TME, and inactivating MYC reduces PD-L1 expression, which enhances the antitumor response." (PMID 40647402, 2025). "Nonetheless, investigators detect MYC and BOP1 co-expression in hepatocellular carcinoma, and we observe MYC and BOP1 co-expression in some TNBC." (PMID 38473786, 2024). "Moreover, one of the most prevalent genetic events during the onset and progression of hepatocellular carcinoma (HCC) is c-MYC overexpression." (PMID 39471843, 2024). "For instance, dual inhibition of MYC targets PD-L1 and CTLA-4 reverses MYC-driven immunosuppression through pro-inflammatory macrophages in hepatocellular carcinoma." (PMID 38390324, 2024). "The MYC oncogene is often dysregulated in human cancer, including hepatocellular carcinoma (HCC)." (PMID 38302473, 2024). "One study showed that TAMs are more prone to glycolytic metabolism in the hepatocellular carcinoma (HCC) tumor microenvironment, which depends on the activation of WNT2b/β-catenin/MYC signaling." (PMID 36966168, 2023). "To determine the clinical value of targeting CHK1 and BRD4 in MYC‐driven HCC, we assessed the role of CHEK1 and BRD4 expression in the pathogenesis of HCC in patients from the Genomic Data Commons (GDC) The Cancer Genome Atlas Liver Hepatocellular Carcinoma (TCGA‐LIHC) data set." (PMID 36684069, 2023). "In a previous study on hepatocellular carcinoma, we reported that transcription inhibition via a CDK7 inhibitor targeting RNA polymerase II drastically decreased MYC cellular level." (PMID 37898690, 2023). "Almost half of these genes (purple-colored genes) were enriched in Hepatitis B, Hepatitis C and Hepatocellular carcinoma pathways including MYC, CD81, CDKN1A, IGF1R and so on which were reported in Hepatocellular carcinoma." (PMID 37051592, 2023). "Cutting-edge research has pointed out that the association of SEs with multiple oncogenes is acquired during hepatocarcinogenesis, and the increase in SEs at MYC and MYCN was observed in hepatocellular carcinoma (HCC) cells." (PMID 35757006, 2022).
hepatocellular carcinoma (continued). "The known mRNA interactors of miR-122 include PKM2, AKT1, MYC, TGFBR1, and SMAD4 in hepatocellular carcinoma, JNK, AP1, and caspases 3/8 in irritable bowel disease, and AKT, PI3K, PCNA, MTDH, PI3K, TRIM29, Bcl-W, CCNG1, and ALDO2 in CRC." (PMID 36499586, 2022). "Enhanced activation of the transcription factor MYC and of the receptor tyrosine kinase MET are among the events frequently occurring in hepatocellular carcinoma (HCC)." (PMID 36433941, 2022). "To further investigate the role of MYC in cholesterol biosynthesis, we knocked down MYC in human osteosarcoma U2OS cells and human hepatoma HepG2 cells." (PMID 33791309, 2021). "For example, ACSL4 was shown to facilitate hepatocellular carcinoma (HCC) development and modulate aberrant lipid metabolism via the c-MYC/SREBP1 pathway." (PMID 34868963, 2021). "To this end, we co-expressed UBL proteins (i.e., MYC-DDK-tagged SUMO-1, HA-tagged SUMO-2, HA-tagged SUMO-3, and MYC-DDK-tagged ISG15) with tagged HBc (i.e., FLAG-tagged or HA-tagged, depending on the used UBL protein) in Huh7 hepatocellular carcinoma cells." (PMID 33256078, 2020). "Upregulation of FAM83H is mediated by binding of MYC at FAM83H promoter and is characteristic of hepatocellular carcinoma cells." (PMID 33175867, 2020). "In hepatocellular carcinomas, FAM83H is transcriptionally regulated by the oncogene MYC, and MYC-FAM83H signaling is involved in the proliferation of cells by affecting the expression of p27 and cyclin D1." (PMID 31215499, 2019). "Genes up-regulated in hepatocellular carcinoma (HCC) from MYC and E2F1 double transgenic mice." (PMID 27732959, 2016). "For example, IGF2BP1 is involved in liver carcinogenesis by binding to and stabilizing the c-MYC and MKI67 mRNAs, and it is an important pro-tumorigenic factor for hepatocellular carcinoma." (PMID 27588393, 2016). "MYC was also found to be destabilized by miR-363-3p through directly targeting and inhibiting USP28 in hepatocellular carcinoma, pointing to a putative role for miR-363-3p in contribution to carcinogenesis and establishment of stemness features." (PMID 27816053, 2016). "Since BTC f exhibits high specificity for the c-MYC quadruplex and the c-MYC gene is overexpressed in liver carcinoma HepG2 cells, the effect of BTC f and the less potent BTC c on transcriptional regulation c-MYC gene was studied in HepG2 cells." (PMID 26286633, 2015). "Among those genes found to be down-regulated following ATIII treatment were JUN and MYC, which are known to be important factors in the pathogenesis of HCV-related hepatocellular carcinoma." (PMID 23031791, 2012). "Of note, overlapping genomic occupancy between TBX3 and β-catenin at relevant cancer-inducing genes, such as MYC, RAS, and STAT1 is also found in hepatocellular carcinoma (HCC) cells, both in cell lines (HepG2 from ENCODE) and in two independent patient-derived HCC biopsies (our data)." (PMID 40343989, 2025). "In hepatocellular carcinoma, RCN1 activates c‐MYC signalling via the IRE1α‐XBP1s pathway." (PMID 39828988, 2025). "Furthermore, DEG data also indicated that MYC, which is highly expressed in chronic liver diseases like MASLD and hepatocellular carcinoma (HCC) 32-34, was significantly increased in mouse liver tissue obtained from HFD+PS-NPs group." (PMID 40607257, 2025). "Most of the trials and recent focus remains in the field of cancer treatment, and indeed the ongoing trials of direct MYC inhibitors are against PDAC, hepatocellular carcinoma, relapsed/refractory hematologic malignancies, and MYC-positive advanced solid tumours." (PMID 38510176, 2024). "It is worth noting that miR-26a could suppress MYC by targeting the Wnt pathway coactivator, cyclin-dependent kinase 8 (CDK8), to inhibit progression and metastasis of hepatocellular carcinoma." (PMID 35120580, 2022).
hepatocellular carcinoma (continued). "PTEN could also enhance β-catenin/MYC signaling and PD-L1 expression in HBV-expressing hepatoma cells, which leads to decreased PD-1 expression, reduces IL-2 secretion, and induces T Cell apoptosis." (PMID 36582540, 2022). "Tumor types, such as stomach adenocarcinoma, lung adenocarcinoma, breast invasive carcinoma, and hepatocellular carcinoma, also exhibit frequent MYC amplification, but not that of MYCN and MYCL gene paralogs." (PMID 34503295, 2021). "Moreover, in hepatocellular carcinoma, increased IL-6 activated the STAT3/c-MYC/miR-25-3p pathway, which resulted in the decreased protein tyrosine phosphatase receptor type O (PTPRO)." (PMID 33413496, 2021). "METTL14 was shown to exert its oncogenic role by regulating MYB and MYC through m6A modification in acute myeloid leukemia (AML), whereas it also suppressed tumorigenesis and metastasis of bladder cancer or hepatocellular carcinoma (HCC)." (PMID 34149792, 2021). "In hepatocellular carcinoma, IGF2BP1 can bind and stabilize c-MYC and MKI67 mRNAs, increase the expression of c-MYC and MKI-67 proteins, which are effective regulators of cell proliferation and apoptosis, and thus participate in regulation of tumor progression." (PMID 33552994, 2020). "Our previous study assessed the c-MYC expression in a collection of human hepatoma cell lines, and found that Hep40, SNU475, and SK-Hep1 cells display the highest levels of c-MYC, whereas PLC, Hep3B, and Huh7 cells exhibited the lowest c-MYC expression." (PMID 33187130, 2020). "Hence, in the current study, we examined the efficacy of a novel mRNA lipid nanoparticle based approach for the in situ delivery and production of IL-12 (IL-12-LNP) in suppressing tumor progression in a primary transgenic mouse model of refractory MYC-driven hepatocellular carcinoma (HCC,)." (PMID 30458889, 2018). "Lastly, in hepatocellular carcinoma, MYC expression does not seem to be predictive of the response of these tumors to JQ1." (PMID 28275007, 2017). "It should be noted, however, that we did not observe any upregulation of the major drivers of hepatocellular carcinoma (HCC) (MYC, IL6, β-catenin) in SO-HFD, nor any signs of tumors or neoplastic lesions." (PMID 26200659, 2015). "In addition to activating SREBP1, MYC directly regulates the expression of key enzymes involved in FA synthesis, such as ACLY, ACC, FASN, and SCD1, which have been shown to drive tumorigenesis in hepatocellular carcinoma (HCC)." (PMID 37700339, 2023). "In particular, we show that miR-138 inhibits MYC expression and suppresses tumor growth of CRC and hepatocellular carcinoma (HCC) cell lines." (PMID 34937878, 2022). "In hepatocellular carcinoma cells, LDHA is overexpressed due to downregulation of miR-383, triggering increased cell proliferation, invasion and glycolysis, MYC, NFκB, HIF-1α-mediated signaling enhances glycolysis in HCC by promoting upregulation of LDHA." (PMID 36686771, 2022). "Similar to m6A and m5C, TRMT6 has been found to mediate the MYC, and also the PI3K/Akt signalling pathway in vitro, thereby downregulating m1A and affecting hepatocellular carcinoma (HCC) prognosis." (PMID 34288419, 2021). "Publicly available ChIP-seq data in human hepatocellular cancer (HepG2) cells and mice livers suggested miR-122 could regulate BCL2 expression indirectly through c-MYC, which was confirmed by siRNA-mediated depletion of c-MYC in Hepatocellular Carcinoma (HCC) cell lines." (PMID 32650615, 2020). "In human hepatocellular carcinoma (HCC) and cholangiocarcinoma (CCA) cells, PHB1 inhibits cell growth and negatively regulates the expression of oncogenes c-MYC, MAFG, and c-MAF." (PMID 30886235, 2019). "Furthermore, a c-MYC-targeting epigenomic controller, OTX-2002, methylates the MYC IGD region and reduces c-MYC expression in hepatocellular carcinoma (HCC) models." (PMID 40333779, 2025).
hepatocellular carcinoma (continued). "In addition, mice with hepatocellular carcinoma (HCC) and liver damage with a high AST level treated with chemotherapy exhibit decreased MYC levels, which can significantly decrease the level of AST and suggest liver function recovery." (PMID 31176361, 2019). "These tumors were diagnosed as hepatocellular carcinoma with the expression of GPC3 and EPCAM, but lacking MYC overexpression." (PMID 39529166, 2024). "GCN5 expression and function therefore accelerates growth of MYC-overexpressing AML, Burkitt’s lymphoma (BL), hepatocellular carcinoma (HCC), colon and non-small cell lung cancer (NSCLC) in cellular systems and, shown in BL, HCC and NSCLC, in vivo mouse models." (PMID 34112237, 2021).